Y_RNA (Y RNA )
Gene: Miscellaneous RNA gene on chromosome 5 (24,910,594 to 24,910,695, forward strand). Ensembl gene ENSG00000199911.
Homologues: Orthologues: chimpanzee Y_RNA (99% identical), macaque Y_RNA (94% identical). Paralogues in human: RNY3P1 (87% identical), Y_RNA (86% identical), RNY3 (85% identical), Y_RNA (85% identical), Y_RNA (84% identical), Y_RNA (83% identical), RNY3P11 (82% identical), Y_RNA (82% identical), RNY3P3 (81% identical), Y_RNA (81% identical), RNY3P9 (80% identical), Y_RNA (80% identical), and 94 more.